EGFR (epidermal growth factor receptor)
Diseases named in the same sentence as EGFR in open-access papers (continued):
Sharing a sentence is not in itself a finding about the gene and the disease.
tumor (continued). "In 18F-afatinib scans (EGFR mutated), contrast was sufficient to distinguish tumor and lung tissue, but lower than for 11C-erlotinib." (PMID 35453931, 2022). "The EGFR gene, located on the short arm of chromosome 7, is commonly mutated in tumor cells of various cancers, though these mutations appear to be most prevalent in NSCLC." (PMID 36010982, 2022). "Following the discovery of EGFR and the association of expression levels with clinical prognosis, a reliable way of quantifying the expression of EGFR in a tumor was sought." (PMID 35455447, 2022). "Several studies have proven the favorable efficacy and safety of VEGFR inhibitors and inhibitors of other tumor-associated targets (including EGFR, FGFR, BRAF, c-Met, HDAC, tubulin, ERα and PIM1) combination therapy in patients with tumors." (PMID 35799213, 2022). "Epidermal Growth Factor Receptor (EGFR) activation is also associated with the upregulation of tumor immune escape markers (PD-1/PD-L1, CTLA4), and is associated with a slight increase in the risk of developing HYD." (PMID 36523973, 2022). "Thanks to the benefit of prognosis, clinicians should require additional EGFR‐plasma mutation testing even though it has been confirmed positive in the tumor tissues." (PMID 34427045, 2022). "First, tumor-specific mutations, particularly activating epidermal growth factor receptor (EGFR) and Ras mutations, appear to predispose cells to ReoV replication and cell death." (PMID 35681452, 2022). "As a result, patients harboring activating EGFR mutations achieve higher tumor responses on EGFR TKI than on conventional chemotherapy." (PMID 36313723, 2022). "They demonstrated that the median PFS and OS were shorter for patients with detectable mutations after three cycles of treatment, underlining the utility of the serial quantitative measurement of EGFR mutations in cfDNA to assess tumor progression." (PMID 36139444, 2022). "The scFv portion of CAR1 and CAR2 was engineered based on the anti-EGFR antibody mAb806, which recognizes the exposed epitope EGFR287–302 overexpressed on the tumor cell surface, as well as mutated EGFR." (PMID 36551506, 2022). "It is important to establish not only that CD109 plays a causal role in SCC tumor growth or metastasis but also to elucidate the molecular mechanisms by which CD109 regulates the oncogenic pathways such as EGFR signaling." (PMID 35954339, 2022). "The specific mechanisms by which pyrotinib targets TSC2-deficient tumor cells were investigated in this study, as well as the interaction between EGFR and CD24." (PMID 36231025, 2022). "Data from literature suggests that Cet has affinity for major EGFR mutations, such as T790, which are found in many tumor cells." (PMID 35208492, 2022). "In several malignancies, such as head and neck carcinomas, EGFR expression, which is normally assessed by immunohistochemistry, has been linked to tumor development and poor survival." (PMID 35455247, 2022). "In a subgroup of NSCLC, tumor growth is driven by epidermal growth factor receptors (EGFR) that harbor an activating mutation." (PMID 36313723, 2022). "Tracer kinetic and biodistribution comparison of 11C-erlotinib, 18F-afatinib and 11C-osimertinib showed that 11C-erlotinib and 18F-afatinib had the highest tumor-to-lung contrast in EGFR mutated tumors." (PMID 35453931, 2022). "It has significantly greater activity against tumor EGFR with mutations del19, L858R, and T790M than wild-type EGFR." (PMID 35223483, 2022). "For instance, Cheng and colleagues mined TCGA to generate an expression signature of EGFR activity, which they associated with tumour sensitivity to EGFR inhibitors and other tyrosine kinase inhibitors." (PMID 35811332, 2022). "In this study, the loss of EGFR mutations was confirmed in the tumor sites after EGFR-TKI administration." (PMID 36505794, 2022). "Preoperative serum tumor markers have been shown to correlate with EGFR mutation and the efficacy of EGFR-TKI therapy." (PMID 35422977, 2022).
tumor (continued). "According to previous studies, overexpression of EGFR is associated with apoptosis, angiogenesis, and formation of tumor vessels." (PMID 36313724, 2022). "For instance, the Aurora kinase A SNP rs6024836 AG + GG is related to an earlier tumor stage if combined with the presence of an EGFR mutation, L858R expression and exon 19 in-frame deletion." (PMID 36011604, 2022). "We found that the dynamic changing patterns of CEA value, variant allele frequency (AF) of EGFR, and tumor size were similar, but the transition time was different." (PMID 35543090, 2022). "Increased phosphorylation of IGF1-R was observed, by immunohistochemistry, in the tumor sample of an EGFR‐mutated NSCLC patient who acquired resistance to osimertinib." (PMID 35463360, 2022). "This retrospective study provides valuable insights into how patients with EGFR mutation-positive NSCLC are treated in everyday clinical practice if an uncommon EGFR tumor mutation is detected." (PMID 35274704, 2022). "18F-FDG metabolic parameters associated with EGFR mutation status in NSCLC reflect the tumor cell glucose metabolism of tumor cells, which have poor sensitivity and are limited by many factors." (PMID 36276079, 2022). "Depatuxizumab mafodotin (Depatux-M) composed of an antibody, ABT-806, targeting tumour specific activated EGFR linked to MMAF." (PMID 36046842, 2022). "Conservation of multiple genes in the relatively large EGFR-mut interactome suggests broad propagation of its oncogenic signals reduces the need for additional tumor promoting mutations." (PMID 36612014, 2022). "Gefitinib, crizotinib and afatinib are kinase inhibitors that are used to treat tumours that exhibit EGFR mutations, ALK fusions and ERBB2/HER2-amplification, respectively." (PMID 35781872, 2022). "In combination with EVAX, JHU083 further decreases Tregs and increases the infiltration of anti‐tumor CD8+ T cells into EGFR‐mutated lung tumors." (PMID 35861366, 2022). "EGFR mutation leads to tumor immune escape and compromises infiltration of tumoricidal effector of T cells." (PMID 36482371, 2022). "Vascular endothelial growth factor (VEGF) plays a critical role in tumor growth and is closely associated with resistance to antineoplastic agents, including EGFR-TKIs." (PMID 36553449, 2022). "Signaling via epidermal growth factor (EGF) leads to tumor cell proliferation, migration, and invasion by causing dimerization of EGFR, a receptor tyrosine kinase." (PMID 35456655, 2022). "Individual treatments are based on patients’ clinic–pathologic characteristics, the tumor’s size and stage, individual somatic mutation status like EGFR, and the tumor’s mutation burden (TMB) status." (PMID 36675677, 2022). "With developments in the molecular genotyping of LC (especially NSCLC), more than 50 tumor-associated RTKs have been identified, such as EGFR, c-MET, ROS1, RET, and ALK." (PMID 36275809, 2022). "Recently, EGFR has been reported to be elevated and correlated with advanced tumor stage and increased risk of metastasis in CRC." (PMID 34991461, 2022). "The most common EGFR variant is a deletion of exons 2–7, EGFRvIII, which often co-occurs with focal EGFR amplification, which together are associated with a more aggressive, immuno-evasive tumour phenotype and worse prognosis." (PMID 35057796, 2022). "EGFR overexpression is associated with increased tumor proliferation, poor differentiation, a high probability of metastasis, and a poor prognosis in these cancers." (PMID 36085575, 2022). "The possible reasons are explained as follows: EGFR mutation was correlated with low tumor metabolic activity of NSCLCs on 18F-FDG PET/CT." (PMID 35800046, 2022). "Recent studies are leaning towards lower PD-L1 expression in EGFR-mutant tumors in comparison to smoking-related cancers, which are well infiltrated with T cells, have higher tumor mutational burden (TMB), and longer survival." (PMID 36291146, 2022).
tumor (continued). "Next-generation sequencing identified 2 uncommon EGFR mutations, G719A and L833V, from tissue and circulating tumor DNA." (PMID 35984165, 2022). "The comparative analysis revealed that the labeling parameters [EGFR(+), HX103(+) or EGFR(+)HX103(+)] showed a statistically significant difference between tumor samples with EGFR-activating mutations and wild-type." (PMID 36376325, 2022). "The expression of tumor antigen target receptors on normal cells/tissues, such as EGFR targeted in this study, causes on-target/off-tumor toxicity, which is a major limitation of ITs for cancer therapy." (PMID 36555466, 2022). "This study aimed to increase the selectivity of anti-EGFR ITs for cells with a higher expression of EGFR compared to cells with low EGFR expression to minimize the risk of on-target/off-tumor toxicity and to expand the therapeutic window of EGFR targeting ITs." (PMID 36555466, 2022). "Osimertinib allows to overcome this issue as it can block EGFR mutated at T790M site; however, resistance to this treatment can also develop after losing tumor cells with T790M." (PMID 35181743, 2022). "EGFR is a member of ErbB family which plays vital roles in many processes associated with tumor development, such as proliferation, survival, migration and apoptosis." (PMID 35504024, 2022). "By targeting two tumour-associated antigens, epidermal growth factor receptor (EGFR) and programmed death ligand 1 (PD-L1), simultaneously with a bispecific two-in-one antibody, high tumour selectivity together with checkpoint inhibition was achieved." (PMID 36439165, 2022). "Given the dismal imaging results and prognosis of the patient, we reasoned that the EGFR mutation would accelerate the development of tumor mass." (PMID 35814475, 2022). "PET/CT using 89Zr-cetuximab allowed the visualization and quantification of tumor 89Zr-cetuximab uptake in cells and animals or other malignancies with EGFR mutations." (PMID 36276079, 2022). "In fact, MDA-MB-231 and A549 cells used in our experiments also bear KRas mutations, and we show that knockdown of either EGFR or ARF6 inhibits tumor growth." (PMID 36224181, 2022). "In the present study, 69% of patients harbouring an exon 19 deletion in their tumor developed EGFR exon 20 p.T790M, while in those with an L858R mutation, 50% had a detectable mutation." (PMID 36292049, 2022). "Propensity scores were estimated using a logistic regression model including the following associated factors for the combination of EGFR mutation and high-grade patterns: smoking index, tumour size and lymphovascular invasion." (PMID 35266536, 2022). "Concordance between NGS and ddPCR performed on the same tumor specimen was 100%, demonstrating that ddPCR is an accurate method for rapid assessment of EGFR mutations." (PMID 35202431, 2022). "This demonstrated the tremendous potential of EGFR variants for use in assessing tumor burden in NSCLC patients." (PMID 35892510, 2022). "These side effects are believed to be caused by interaction of the anti-EGFR targeting drugs with the receptor in other tissues than the tumor." (PMID 36090901, 2022). "In FGFR3-mutated tumor PDXs, an anti-FGFR and anti-EGFR combination therapy improves tumor response compared to FGFR inhibition alone." (PMID 36033544, 2022). "When the drug is in the “on-target” state, an EGFR mutation is the main cause of tumor resistance to the drug." (PMID 35684449, 2022). "The mechanism of resistance for EGFR activation includes increased EGFR expression and increased subsequent ligand production on malignant cells and, lastly, the presence of mutations of EGFR in malignant/tumor cells." (PMID 35978836, 2022). "Several clinical studies demonstrated the presence of low-abundance EGFR T790M mutations in pre-treatment tumor tissue of patients with NSCLC harboring EGFR mutations." (PMID 35326664, 2022).
tumor (continued). "In lung cancer with an EGFR mutations, an increasing body of evidence has shown that exosomes can provide important information regarding tumor initiation, progression and metastasis formation." (PMID 35954442, 2022). "These patients should undergo primary tumor resection followed by tumor profiling, specifically to investigate mutations including those related to the epidermal growth factor receptor (EGFR), which then permits consideration for targeted therapy." (PMID 35267572, 2022). "Age, gender, tumor size, histological subtypes, EGFR mutation, and tumor differentiation grades were significantly associated with the abnormal level of CEA in both univariate and multivariate regression analyses (p < 0.05)." (PMID 35289087, 2022). "Patients with plasma concurrent EGFR mutations are classified into the shedding tumor group and associated with poor performance status, advanced clinical stage, increased metastatic site, and large tumor volume." (PMID 34427045, 2022). "The alterations of EGFR signaling have the potential to produce an ineffective tumor-associated immune microenvironment by upregulating a series of immune suppressors, including inhibitory immune checkpoints, immunosuppressive cells, and cytokines." (PMID 36439487, 2022). "This study shows RNAi treatment against the EGFR caused a knockdown in both the level of immunoreactive EGFR in the human tumor and the vascular density of the tumor, as shown by the level of immunoreactive mouse TfR at the vasculature." (PMID 35745855, 2022). "The plasma and tumor tissue samples at disease progression were subjected to EGFR mutation analysis using the ddPCR platform." (PMID 36232650, 2022). "Tumour cells with oncogenic activating mutations in the EGFR (epidermal growth factor receptor), ALK (anaplastic lymphoma kinase) or RET (rearranged during transfection) kinases were found to reduce MHC-I expression." (PMID 35343573, 2022). "Mutations in the EGFR gene can lead to continuous activation of its downstream signaling pathways, promoting tumor cell proliferation and inhibiting tumor cell apoptosis." (PMID 35418149, 2022). "The radiological burden of LM significantly correlated with CSF tumor cell counts (p = 0.013) with higher CSF tumor cell counts predicting a higher detection sensitivity of EGFR mutation (p = 0.042)." (PMID 35740489, 2022). "Immunotherapy as a first line option is to be avoided when the tumor harbors some driver mutations, most notably EGFR activating alterations, due to inefficacy and heightened toxicity." (PMID 36136862, 2022). "It belongs to a subfamily of EGFR and is overexpressed in 80% of tumor samples of GBMs and is associated with poor survival." (PMID 36305981, 2022). "In a comprehensive analysis of ctDNA in mCRC patients, patients with EGFR-ECD mutations displayed striking tumor heterogeneity, with 91% harboring distinct multiple mechanisms of resistance." (PMID 36818675, 2022). "Studies have shown that secondary EGFR mutations are rare in NSCLC tumor cells prior to treatment with TKI therapies, suggesting that these mutations are selected for after exposure to TKIs." (PMID 36010982, 2022). "EGFR is a main regulator of epithelial tissue development, but hyperactivity of EGFR signaling associates with enhanced tumor growth, migration, and invasion and promotes the formation of metastases." (PMID 36359732, 2022). "Activating mutations were identified in tumor samples including EGFR L858R, EGFR T790M, EGFR exon 19 deletion, ERBB2 amplification, ALK fusion, KRAS G12C." (PMID 35123506, 2022). "In our group, there was a 100% reproducibility between PCR-detected EGFR variants and tumor tissue NGS results, and a 92.3% concordance between tumor tissue PCR and NGS and plasma NGS results, similar to other studies." (PMID 36551569, 2022). "EGFR is associated with tumor cell proliferation, angiogenesis, tumor invasion, metastasis, and inhibition of apoptosis." (PMID 35342754, 2022).
tumor (continued). "Tumor growth is greatly reduced or suppressed by the presence of the waved (wa2) mutation of the epidermal growth factor receptor (EGFR), but it can be efficiently induced by mechanical irritation or wounding." (PMID 36429119, 2022). "Then, the top-ranked features and four clinical features (age, gender, smoking, and tumor family history) were input into the SVM classifier to establish a radiomics signature that predicts EGFR mutation status in the training group (n = 514)." (PMID 36052262, 2022). "Rearrangement of ALK accounts for 4%–7% of NSCLC patients, only second to EGFR mutation, which promotes the growth and proliferation of malignant tumor cells." (PMID 35734411, 2022). "A multicenter phase II trial (the CHRONOS trial) of anti-EGFR rechallenge therapy with panitumumab guided by monitoring of the mutational status of RAS, BRAF, and EGFR in circulating tumor DNA (ctDNA)." (PMID 36147443, 2022). "With tumor tissue results as the reference, the sensitivity and the specificity for EGFR T790M mutation in plasma samples were 81.82% and 91.85%, respectively." (PMID 36776375, 2022). "In different NSCLC cells mutated in the epidermal growth factor receptor (EGFR) volasertib reversed resistance to erlotinib, causing G2/M arrest and apoptosis, and reduced tumor growth in vivo." (PMID 35719948, 2022). "The second generation of EGFR-TKIs contains Afatinib and Dacomitinib, which can synergistically inhibit EGFR, HER2 and HER4, while also inhibiting tumor cells with the most common exon 19 deletion mutation and exon 21 (L858R) mutation in the EGFR gene." (PMID 35372042, 2022). "The interruption of EGFR signaling by afatinib would lead to substitution by cancer-associated fibroblasts and tumor cells secreting HGF and SDF-1α14,16,17." (PMID 35039644, 2022). "Recent study also suggested that tumor with EGFR L858R mutation have higher level of PD-L1 expression and are positively associated with inflammatory phenotype." (PMID 35296087, 2022). "Next generation sequencing (NGS) technology has allowed improved detection of cell free DNA (cfDNA) or circulating tumor DNA (ctDNA) and are the only clinically validated methods as companion diagnostics for EGFR mutated NSCLC." (PMID 35209919, 2022). "The frequency of EGFR-activating mutations in tumor tissue also varies among different global demographics, with 30–40% of patients with NSCLC from East Asia exhibiting these mutations, but only 5–15% of patients of non-Asian origin." (PMID 36185288, 2022). "EGFR amplification results in enhanced protein abundance on the membrane of tumor cells, while EGFR mutation gives rise to abnormal protein products." (PMID 35016696, 2022). "Testing two tumor lines from patients with naturally occurring PTPRH mutations revealed a sensitivity to EGFR inhibitors." (PMID 36054194, 2022). "One possible explanation is that each tumor with EGFR mutations has different innate drug-resistant cell clone profiles." (PMID 35326664, 2022). "Recently, the expression of genes such as TYMS, RRM1, TUBβ3, and EGFR was found to be associated with tumor histological type (at p < 0.05) and progression-free survival rates." (PMID 36294786, 2022). "Regarding tumor genomic alterations, the EGFR mutations were detected in 23.3% of the patients, and as expected, they were more prevalent in non-smokers than in smokers." (PMID 36644085, 2022). "A substantial body of evidence has demonstrated that overexpression of EGFR, as well as its tumour-restricted mutant form (EGFR variant III/vIII) plays key driver roles in GBM." (PMID 36046842, 2022). "The discrepancy between the survival benefit of erlotinib plus bevacizumab and osimertinib plus bevacizumab possibly reflects tumor heterogeneity caused by different EGFR-TKIs." (PMID 36482474, 2022).